TNF (tumor necrosis factor)
Diseases named in the same sentence as TNF in open-access papers (continued):
Sharing a sentence is not in itself a finding about the gene and the disease.
falciparum malaria (24 papers, 2006 to 2025). "In falciparum malaria TNF has been implicated in ICAM-1 up-regulation although infected red blood cells alone are sufficient to produce this effect." (PMID 22305466, 2012). "Falciparum malaria was associated with higher levels of circulating plasma TNF-α than mixed-species infections." (PMID 22973442, 2012). "TNF has been associated with accelerated parasite clearance in falciparum malaria and clinical use of TNF inhibitors increases the risk of hyperparasitemia following malaria infection." (PMID 19390618, 2009). "This study investigates the association between two APOA1 gene polymorphisms (G-75A and C+83T), APOA1 levels, and inflammatory markers (tumor necrosis factor-alpha and interleukin-6) in Nigerian children with uncomplicated Plasmodium falciparum malaria." (PMID 40061813, 2025). "Elevated serum TNF-α levels have been reported to be directly correlated with the severity of Plasmodium falciparum malaria." (PMID 35743265, 2022). "We therefore, determined Cytokine profiles (IFN-γ, TNF-α, IL-6, TGF-β and IL-10) associated with Plasmodium falciparum malaria and soil borne helminth co-infections among patients attending Kampala International University Teaching Hospital in Uganda." (PMID 29560020, 2018). "Additionally, the serum levels of sTNF-R1 and sTNF-R2, which act as binding proteins for TNF, were elevated in patients with acute Plasmodium falciparum malaria compared to the levels in convalescent children and in healthy controls." (PMID 17997848, 2007). "Cytokines such as TNF and IL-1, both increased in a wide range of systemic inflammatory diseases, including falciparum malaria, can induce a late-onset, but long-acting wave of a cytokine termed the high mobility group box 1 (HMGB1) protein, which prolongs and amplifies inflammation." (PMID 17029647, 2006). "Furthermore, TNF, IL-1, IL-6, etc., inflammatory genes are over-expressed in falciparum malaria." (PMID 36239109, 2022). "The balance between Th1 cytokines (TNF-α, IFN-γ) and Th2 cytokines (IL-10, IL-4) has been shown to be critical in the development of severe falciparum malaria with IL-10 shown to downregulate the functional activity and the production of TNF-α in Pf infection." (PMID 33604551, 2019). "Contrary to the recent suggestion that P. vivax elicits more inflammation than P. falciparum, we found higher IL-10/TNF-α, IL-10/IFN-γ and IL-10/IL-6 ratios, but similar inflammatory cytokine responses per parasitized red blood cell, in vivax compared to falciparum malaria." (PMID 22973442, 2012).
metastatic cancer (24 papers, 2004 to 2024). A carcinoma which has spread from the original site of growth to another anatomic site. "We have demonstrated here, for the first time, an additional role for osteocyte primary cilia and the associated IFT88 pathway, in controlling TNF‐α secretion and altering metastatic cancer cell behavior." (PMID 37967351, 2024). "Increased blood levels of TNF-α have been associated in metastatic cancer patients." (PMID 33805444, 2021). "In metastatic cancer, these pathways are activated by pro-inflammatory cytokines such as interleukin 6 (IL-6), interleukin 1 (IL-1), tumor necrosis factor alpha (TNF-α), and interferon gamma (IFN-γ)." (PMID 35994202, 2022). "The use of TNF-α is applicable for the patients with cancer with resistance because the level of TNF-α is highly increased in patients with advanced and metastatic cancer, and it is associated with cancer progression." (PMID 32784919, 2020). "Pathological regulation of TNF-α has been related to primary and metastatic cancer promotion, directly or via a complex network of cytokines, chemokines, and matrix metalloproteases." (PMID 19904265, 2009). "TNF-α was significantly elevated in patients with metastatic cancer compared with the two groups of patients with localised disease and controls, and was correlated with increasing PSA." (PMID 15150588, 2004). "Therefore, clinical efficacy, particularly for metastatic cancers, would require sufficient endogenous TNFα at the tumor site to cooperate with exogenously administered IAP antagonists." (PMID 27129149, 2016). "Moreover, HBV replication promoted immune cells to secrete tumor necrosis factor a (TNF-a), which also killed metastatic cancer cells." (PMID 25265536, 2014). "This study suggests that TNF autovaccination is a cheaper and highly efficient alternative that can block TNF and reduce metastasis in vivo and trials with TNF autovaccination are already underway in patients with metastatic cancer." (PMID 15026813, 2004). "Metastatic cancer cells seem to acquire characteristics that predispose to the Warburg effect and in some manner this correlates with their ability to activate the aerobic glycolysis after TNF stimulation; surprisingly however, also RWPE show a Warburg phenotype after TNF stimulation." (PMID 28270771, 2017). "Our results indicate that both the conventional anti-TNF monoclonal antibody treatment and TNF autovaccination are successful in reducing the number and size of lung metastases in this model and supports the use of these agents in clinical trials in patients with metastatic cancer." (PMID 15026813, 2004). "The VCAM pathway, GDF pathway, MIF pathway, TNF pathway, CD137 pathway and ITGB2 pathway specifically appeared in metastatic cancer." (PMID 38365757, 2024). "For example, Cx43-GJs allow brain metastatic cancer cells transferring cGAMP to astrocytes, leading to the activation of the STING pathway and the subsequent production of IFN-α and tumor necrosis factor by the cGAMP-receiving astrocytes." (PMID 33066331, 2020). "We also examined whether ampelopsin could suppress TNF-α-stimulated NF-κB signaling, because the TNF-α/NF-κB pathway has been known to enhance migration, invasion, and tumorigenesis in metastatic cancer." (PMID 34451892, 2021). "In addition, in the case of advanced or metastatic cancer, TNF-α was increased, so we thought that TNF-α treatment would be more suitable in the in vivo model." (PMID 33233701, 2020). "Since TNF is known to induce PDGF signaling, we decided to explore the possibility that VEGF-C has a novel role in inflammatory arthritis similar to its role in metastatic cancer." (PMID 17997858, 2007). "Furthermore, TNF-α also led to upregulation of αvβ3 integrin and a 3-fold increase in expression of the cell–cell adhesion molecule N-cadherin in HEI-193 cells, 2 cell-surface proteins whose overexpression is observed in metastatic cancers." (PMID 38887507, 2024).
muscle atrophy (24 papers, 2014 to 2025). The loss of muscle tissue due to inactivity or disease. "Muscle atrophy in postmenopausal women is caused by estrogen deficiency and a variety of inflammatory factors, including tumor necrosis factor alpha (TNFα)." (PMID 35455387, 2022). "We presented several findings from a range of studies which may indicate that proinflammatory markers (e.g., TNF-α and IL-6) may be responsible for the activation of pathways associated with muscle atrophy in poststroke patients (e.g., UPS system)." (PMID 27647951, 2016). "For instance, IL-6 has been reported to induce skeletal muscle atrophy, while TNF-α released by macrophages promotes muscle pyroptosis." (PMID 40940715, 2025). "In the present study, we demonstrated that RCE exerts potent anti-inflammatory and antioxidant effects in both TNF-α-stimulated L6 myotubes and an immobilization-induced muscle atrophy model in mice." (PMID 41228534, 2025). "The hSkMOs we developed offer a robust platform to model senescence‐induced muscle atrophy, as well as the regenerative potential of SCs, in response to inflammatory stimuli such as TNF‐α." (PMID 40810394, 2025). "Muscle atrophy is strongly linked to an increase in the generation of inflammation-inducing cytokines, including TNF-α (tumor necrosis factor-alpha), IL-1 (interleukin-1), IL-6 (interleukin-6), and IFN-γ (interferon-gamma)." (PMID 38732255, 2024). "Muscle atrophy is often accompanied by elevations in inflammatory cytokines such as interleukin-6 (IL-6) and tumor necrosis factor-alpha (TNF-α), which induce alterations in the body’s consumption of proteins, lipids, and carbohydrates." (PMID 37589754, 2023). "A recent study also demonstrated that the application of pyrrolidine dithiocarbamate (PDTC), a NF-κB inhibitor, provides a potential therapeutic strategy for TNF-α-induced muscle atrophy." (PMID 36466088, 2022). "Myogenin has been found to induce muscle wasting under different conditions, including denervation, spinal muscle atrophy, starvation, and tumor necrosis factor α-induced atrophy (TNF-α)." (PMID 36362238, 2022). "Both denervation-induced muscle atrophy mouse model and TNFα-treated C2C12 cells/primary myogenic cells were used to investigate TNFα levels in atrophying muscles and its inhibition on myotube formation in vitro." (PMID 36618945, 2022). "Our results showed that anti‐oxidative enzyme (SOD, CAT and GSH‐Px) activity was decreased, and ROS and MDA productions were increased in CKD‐induced muscle atrophy, and in TNF‐α‐induced C2C12 cells." (PMID 32910538, 2020). "Muscle atrophy was observed in CM-treated myotubes due to the increase in inflammatory cytokines including TNF-α, interleukin-6, interleukin-1β and interferon-γ." (PMID 29258243, 2017). "Therefore, we examined the expression levels of core proteins in the TNF‐α/NF‐κB signaling pathway to elucidate the mechanism by which puerarin delays the development of muscle atrophy in dexamethasone‐induced sarcopenic mice." (PMID 40255543, 2025). "One of the important features of muscle atrophy is the destruction of the neuromuscular junction, which leads to motor neuron depletion and the accumulation of macrophages, as well as other immunological elements, such as TNF-α, which plays a principal role in the relapsing of motor neurons." (PMID 38785754, 2024). "We noted intrathecal Ad-irisin attenuated pain sensitization and gastrocnemius muscle atrophy by modulating the level of irisin in CSF, and the expression of neuronal FNDC5/irisin and TNFα in the spinal cord." (PMID 33096842, 2020). "Our molecular docking results showed that Aloin A had good binding interactions with HSP90AA1, AKT1, CTNNB1, BCL2L1, RELA, TNF, AKT3, the ranging from −7.9 to −8.9 kcal/mol, suggesting that Aloin A stably combined with these proteins for attenuating cancer related muscle atrophy." (PMID 38180061, 2023).
muscle atrophy (continued). "We also discovered that inflammation-related genes (TNF-, IL-6, and IL-1b) showed no changes even after 5 weeks of EVs-Cas9-29b therapy in IMO- and Den-induced muscle atrophy which is coincidentally the endpoint of the treatments." (PMID 35761332, 2022).
necrotizing enterocolitis (24 papers, 2009 to 2026). Necrotizing enterocolitis (NEC) is a devastating disease that affects mostly the intestine of premature infants. "Both IGF1 and TNF-α have been implicated in various complications associated with prematurity, such as bronchopulmonary dysplasia and necrotizing enterocolitis, primarily through their roles in inflammation and growth regulation." (PMID 39194926, 2024). "Administration of adipose-derived stem cells before the onset of the disease lowers the initial levels of IL-6 and TNF-alpha in the rat model of necrotizing enterocolitis." (PMID 40724804, 2025). "In vivo experiments showed that glycyrrhizin reduced the expression of HMGB1, TNF‐α and IL‐1β in osteoarthritic cartilage, as reported in keratitis and necrotizing enterocolitis." (PMID 34953035, 2022). "It was shown that blocking TNF-α with infliximab has beneficial effects on experimental necrotizing enterocolitis and hypoxic intestinal injury." (PMID 32651971, 2021). "The bacterial flora of neonatal necrotizing enterocolitis patients contain significantly higher amounts of Bacteroides, which is accompanied by an enhancement of TNF-α, and Bacteroides vulgatus induces NF-κB activation and pro-inflammatory gene expression in intestinal epithelial cells." (PMID 31275120, 2019). "TNFα and IFNγ are key cytokines mediating innate and adaptive immune cell activity in the gut during bacterial infection and in necrotizing enterocolitis." (PMID 29110754, 2017). "In addition, TNFα mRNA transcripts can be detected in Paneth cells under normal conditions, and are expressed at much higher levels by these cells in patients with necrotizing enterocolitis." (PMID 23977323, 2013). "Studies have reported that PAF and TNF-α can mutually cooperate with each other to promote the progress of inflammatory response, such as acute lung injury, monilia infection, and necrotizing enterocolitis." (PMID 23209346, 2012). "Previous research has demonstrated that the exogenous administration of AI-2 contributes to a reduction in intestinal TNF-α and an increase in IL-10, resulting in the attenuation of the inflammatory responses in mice with necrotizing enterocolitis (NEC)." (PMID 38369503, 2024). "Recent research has also shown that SFN (20 mg/kg/day) mitigates necrotizing enterocolitis (NEC) by reducing the expression of IL-1β, IL-8, IL-10, IL-6, and TNF-α, thereby decreasing apoptosis in NEC-induced mice." (PMID 38671854, 2024). "Due to its anti-TNF activity, PTX has been studied in animals and human adults and newborns to ameliorate inflammatory conditions such as BPD, meconium aspiration, necrotizing enterocolitis, and hypoxic ischemic encephalopathy." (PMID 29715306, 2018). "Furthermore, TNF-α is also on the basis of acute inflammatory preterm birth complications such as bronchopulmonary dysplasia (BPD), retinopathy of prematurity (ROP), and necrotizing enterocolitis (NEC)." (PMID 25629558, 2015).
pemphigus (24 papers, 2008 to 2025). Pemphigus is a group of rare autoimmune diseases that cause blistering of the skin and mucous membranes (mouth, nose, throat, eyes, and genitals).This conditioncan occur at any age, but often strikes people in middle or older age. "Furthermore, polymorphisms of genes encoding several cytokines, such as IL-4, IL-6, IL-10, TNF-α, and transforming growth factor-β have been reported in pemphigus patients compared to healthy controls, suggesting a potential involvement in the pathogenesis of this disease." (PMID 38213911, 2023). "Phenol groups trigger pemphigus by releasing cytokines such as tumor necrosis factor-alpha (TNF-α) and interleukin-1 alpha (IL-1α) and activating the complement system and proteases, causing acantholysis (e.g., aspirin, rifampin)." (PMID 40599502, 2025). "One systematic review of cytokine research in pemphigus revealed elevated levels of TNF-α, TGF-β, interleukin (IL)-8, IL-10, IL-12, IL-17, and IL-21, along with reduced levels of IL-2 and IL-23." (PMID 39463588, 2024). "Possible mechanisms of phenol-induced pemphigus include the induction of IL-1α and TNF-α release by keratinocytes." (PMID 38213911, 2023). "A case-control study had the objective to estimate the initial serum levels of TNF-alpha in pemphigus patients and compare them with history of stress, body surface area affected, disease severity, and disease outcome." (PMID 36703956, 2022). "TNF-α, IL-6, IFNs, IL-17, IL-21, and IL-23 among others are known for their contribution to inflammatory process also in the course of pemphigus." (PMID 32170648, 2020). "Although TNF-α has been suggested to play a role in inducing acantholysis in pemphigus, results on the effectiveness of TNF-α inhibitors, such as etanercept and infliximab, in AIBDs are conflicting." (PMID 33117178, 2020). "We investigated the plasma concentrations of the APC-derived immunomodulatory cytokine IL-27 and the pro-inflammatory cytokines IL-6 and TNF-α in active and remitting pemphigus patients, MG patients and HC." (PMID 26872212, 2016). "Although we live in the era of TNF-alpha inhibitors, the role of these agents in pemphigus therapy is still controversial, as only a limited efficacy has been proved." (PMID 25896794, 2015). "In most published studies, the authors found an increasedlevel of TNF-α in the active stage of pemphigus." (PMID 18584045, 2008). "In experimental models, it was also demonstratedthat IL-1α and TNF-α were able to activate C3 mRNA in keratinocytes cultureafter stimulation with pemphigus antibodies obtained from PV patients." (PMID 18584045, 2008). "This suggests that pre-treatment serum TNF-α levels may be an important prognostic indicator for pemphigus in correlation with stress levels." (PMID 39502648, 2024). "However, biological therapy does play an important role in the management of some oral diseases, in particular, rituximab in pemphigus and anti-TNF-α agents in recalcitrant OFG." (PMID 38388611, 2024). "Tumor necrosis factor alpha (TNF-α) inhibitors can be used in recalcitrant pemphigus cases." (PMID 38957191, 2023). "TNF- α, IL-6, IL-15, IL-10, IL-12, are involved in the mechanism of pemphigus lesions formation." (PMID 36613766, 2022). "Consistent with human studies, TNF was also upregulated in pemphigus lesional skin." (PMID 34660634, 2021). "Likewise, several studies have reported increased levels of IL-8, IL-6, and TNF-α in pemphigus, which were also in the ceRNA network." (PMID 34531933, 2021). "In our study we noticed a strong correlation of IL-27 plasma concentrations with TNF-α in pemphigus patients which might support an additional pro-inflammatory function of IL-27 in pemphigus as well." (PMID 26872212, 2016). "Presence of a chronic inflammatory background may represent a link between pemphigus, cardiovascular comorbidities and a lower overall survival, due to the direct involvement of various cytokines, such as TNF alpha and IL-6." (PMID 25896794, 2015).
pemphigus (continued). "Consistent with this idea, inhibition of the action of some cytokines, in particular FasL and TNF-α, can inhibit acantholysis in experimental models of pemphigus, and a beneficial action of new TNF-α blocking biological agents in patients has also been reported." (PMID 20585604, 2010). "Moreover, experimental studiesrevealed that synergistic cooperation of pemphigus antibodies with Fas-L and TNF-α results in acantholysis." (PMID 18584045, 2008). "Furthermore, the plasma concentrations of TNF-α were also increased in active pemphigus and correlated very strongly with the plasma concentrations of IL-27 (rs = 0.87) supporting a pro-inflammatory function of IL-27 in pemphigus." (PMID 26872212, 2016). "Thus, TNF may play a mediator role in pemphigus lesions by increasing epithelial damage." (PMID 34660634, 2021). "We also found a negative correlation between TNF-α level and pemphigus antibodies titer in the patients from the remission group (rS = −0.47303; P < .02)." (PMID 18584045, 2008). "When analysing correlations between titer ofcirculating pemphigus antibodies andserum concentrations of the examined cytokines, we found a negative correlationbetween TNF-α level and antibodies titer in the patientsfrom the remission group (rS = −0.47303; P < .02)." (PMID 18584045, 2008). "Interestingly, in the remitting pemphigus patients (n = 3) neither IL-27 nor IL-6 or TNF-α could be detected in distinct amounts." (PMID 26872212, 2016).